PVR (PVR cell adhesion molecule)
Description:
Mediates NK cell adhesion and triggers NK cell effector functions. Binds two different NK cell receptors: CD96 and CD226. These interactions accumulates at the cell-cell contact site, leading to the formation of a mature immunological synapse between NK cell and target cell. This may trigger adhesion and secretion of lytic granules and IFN-gamma and activate cytotoxicity of activated NK cells. May also promote NK cell-target cell modular exchange, and PVR transfer to the NK cell. This transfer is more important in some tumor cells expressing a lot of PVR, and may trigger fratricide NK cell activation, providing tumors with a mechanism of immunoevasion. Plays a role in mediating tumor cell invasion and migration. (Microbial infection) Acts as a receptor for poliovirus. May play a role in axonal transport of poliovirus, by targeting virion-PVR-containing endocytic vesicles to the microtubular network through interaction with DYNLT1. This interaction would drive the virus-containing vesicle to the axonal retrograde transport. (Microbial infection) Acts as a receptor for Pseudorabies virus. (Microbial infection) Is prevented to reach cell surface upon infection by Human cytomegalovirus /HHV-5, presumably to escape immune recognition of infected cell by NK cells.
Synonyms: NECL-5; CD155; PVS; HVED; NECL5; Tage4
Tractability: Small molecule: a structure with a bound ligand is known; it has a binding pocket of medium quality. Antibody: its Gene Ontology location is reachable by antibodies, with high confidence; UniProt places it where antibodies can reach, with medium confidence; UniProt predicts a signal peptide or a membrane-spanning region; the Human Protein Atlas places it where antibodies can reach. PROTAC: ubiquitination databases record sites on it; its protein half-life has been measured.
Gene: Protein-coding gene on chromosome 19 (44,643,798 to 44,666,162, forward strand). Ensembl gene ENSG00000073008.
Subcellular location: Cell membrane (Isoform Alpha); Cell membrane (Isoform Delta); Secreted (Isoform Beta); Secreted (Isoform Gamma)
Subcellular location (Human Protein Atlas): Nucleoplasm; Plasma membrane; Vesicles; Predicted to be secreted
Pathways (Reactome):
Cell-Cell communication: Nectin/Necl trans heterodimerization
Immune System: Immunoregulatory interactions between a Lymphoid and a non-Lymphoid cell
Gene Ontology:
Molecular function: cell adhesion molecule binding; protein binding; receptor ligand activity; cell adhesion mediator activity; signaling receptor activity; virus receptor activity
Biological process: natural killer cell mediated cytotoxicity; negative regulation of natural killer cell mediated cytotoxicity; positive regulation of natural killer cell mediated cytotoxicity; positive regulation of natural killer cell mediated cytotoxicity directed against tumor cell target; susceptibility to natural killer cell mediated cytotoxicity; susceptibility to T cell mediated cytotoxicity; heterophilic cell-cell adhesion; homophilic cell-cell adhesion; signal transduction; symbiont entry into host cell
Cellular component: cell surface; focal adhesion; membrane; plasma membrane; adherens junction; cytoplasm; extracellular region
Genetic constraint (gnomAD): Loss-of-function variants: 35 observed, 40.63 expected, observed/expected ratio (o/e) 0.86, 90% interval 0.66 to 1.14. The upper end of that interval is the gene's LOEUF score, 1.14, which puts it in group 5 of 6, group 1 being the genes least tolerant of losing a copy. Missense variants: 476 observed, 547.48 expected, observed/expected ratio (o/e) 0.87, 90% interval 0.81 to 0.94. Synonymous variants: 224 observed, 232.88 expected, observed/expected ratio (o/e) 0.96, 90% interval 0.86 to 1.08.
Homologues: Orthologues: chimpanzee PVR (98% identical), macaque PVR (90% identical), rabbit PVR (57% identical), dog PVR (56% identical), rat Pvr (40% identical), mouse Pvr (40% identical), zebrafish si:ch73-22o12.1 (31% identical), zebrafish pvrl2l (27% identical), zebrafish si:ch211-141e20.2 (20% identical), zebrafish si:ch211-222f23.6 (18% identical), Drosophila melanogaster Fas3 (18% identical), zebrafish zgc:113337 (16% identical), and 3 more. Paralogues in human: NECTIN2 (48% identical), NECTIN1 (28% identical), NECTIN3 (25% identical), NECTIN4 (23% identical), CADM1 (20% identical), CADM2 (20% identical), CADM3 (20% identical), CADM4 (19% identical), CD200 (13% identical), CRTAM (13% identical), CD226 (12% identical), TIGIT (9% identical), and 2 more.
Diseases named in the same sentence as PVR in open-access papers:
PVR is named in the same sentence as 170 diseases in open-access papers, as found by Europe PMC text mining. Sharing a sentence is not in itself a finding about the gene and the disease. The quoted sentences say what the papers report.
melanoma (86 papers, 2012 to 2026). A malignant, usually aggressive tumor composed of atypical, neoplastic melanocytes. "PVR overexpression is associated with poor prognosis in melanoma, colorectal, lung, and pancreatic cancers." (PMID 32506804, 2020). "Breast, ovarian, endometrial, and prostate cancers express PVRL2 predominantly, while melanoma, esophageal, and colorectal cancers express PVR predominantly." (PMID 39156900, 2024). "PVR is overexpressed in melanomas compared to melanocytes and benign nevi and correlates with known poor prognostic factors." (PMID 39156900, 2024). "In this context, a recently reported dual inhibitor of CD47/SIRPα and TIGIT/PVR pathways merits further study for utility as an ICI in melanoma." (PMID 36768931, 2023). "As a consequence of the BRAF inhibitor treatment, activating ligands MICA, ULBP3 and PVR are decreased on melanoma cells, thus contributing to diminished NK cell activation and further support of immune escape." (PMID 34572949, 2021). "PVR is overexpressed by some tumor entities including melanoma, glioblastoma, colorectal and pancreatic carcinoma." (PMID 29855615, 2018). "Although no detectable immunohistological staining for PVR was found in normal tissue, PVR expression was elevated in some primary tumors including colorectal, prostate, renal and pancreatic carcinoma, melanoma as well as glioblastoma." (PMID 29855615, 2018). "PVR is a vital ligand recognized by DNAM1 in inhibiting NK cell-mediated melanoma metastasis." (PMID 39156900, 2024). "CD155, also called Poliovirus receptor (PVR), is widely expressed on epithelial cells, endothelial cells, nerve cells, and fibroblasts, and is upregulated in some human malignancies such as colon cancer and melanoma." (PMID 36985819, 2023). "High PVR expression was found to be positively associated with an increased PD−1 + CD8+ T cells proportion within the tumor, which was also associated with early progression in melanoma patients treated with anti-PD1." (PMID 36552960, 2022). "A combination of cDNA arrays, immunohistochemistry, serology and immunological methods recently identified a combined overexpression signature of MICA, ULBPs and PVR in early-passage melanoma cells as compared to autologous normal melanocytes from the surrounding, intact skin of melanoma patients." (PMID 26427039, 2015). "Furthermore, researchers have demonstrated that the silencing of PVR in melanoma increased sensitivity to combined anti-PD1/CTLA4 therapy, suggesting that targeting PVR could serve as a complement to current immunosuppressive therapies." (PMID 36552960, 2022). "MDA-MB-231 cells express many of these ligands, and they were present in purified MDA-MB-231 (breast cancer), Gli36 (glioblastoma) and B16-F1 (melanoma) blebbisomes, including PD-L1, PD-L2, B7-H3, VISTA, PVR and HLA-E." (PMID 39984653, 2025). "PVR is considered to be a modulator of the immune response in cancers such as LUAD, colorectal cancer, melanoma, etc.." (PMID 39120585, 2024). "In vivo, soluble PVR inhibits DNAM1-mediated NK cell cytotoxic activity and promotes melanoma lung metastasis." (PMID 39156900, 2024). "Both CD112 (Nectin-2), as well as CD155 (poliovirus receptor, PVR), which are widely expressed by cancer cells such as melanoma, are recognized by DNAM-1." (PMID 38057843, 2023). "The analysis of large panels of melanoma cells showed that ligands for NKG2D (MICA/B, ULBPs) and DNAM-1 (PVR, Nectin-2) are widely expressed by melanoma cells." (PMID 34712615, 2021). "In support of a PVR blockade strategy, studies in acute myeloid leukemia (AML) and melanoma cell lines as well asin vivo murine tumor models resulted, respectively, in the activation of anti-tumoral cell types and avoidance of metastases." (PMID 32489646, 2020).
melanoma (continued). "Our findings are in line with a recent report in which melanoma cells expressing PVR control anti-melanoma CTL responses via the interaction between TIGIT and PVR in the effector phase by a suppression of cytokine release from melanoma-specific CTL." (PMID 29855615, 2018). "CD155, also known as poliovirus receptor (PVR), and poliovirus receptor-related 2, also known as CD112 or nectin-2, are expressed on a variety of tumor tissues, including leukemias, ovarian cancer, neuroblastoma, melanoma, and glioblastoma." (PMID 35011583, 2021). "TIGIT binds two ligands, CD112 (nectin-2, also known as PRR2 or PVRL2) and, with much higher affinity, CD155 (PVR or Necl-5), both identified on APCs, T cells and a variety of non-hematopoietic cell types including melanoma cells." (PMID 34572799, 2021). "Moreover, we demonstrate that tumor-relevant genes, such as FosB, WEE1, PVR, MAP1LC3B, and LGALS3, are deregulated in melanoma by direct regulation via c-Jun5." (PMID 31378787, 2019). "This, together with the frequent expression on melanoma cells of ligands recognized by major activating NK receptors (including MICA/B, ULBPs, PVR, Nectin-2 and B7H6), suggests that NK cells may indeed represent important effectors against this tumor." (PMID 27563819, 2016). "Expression of PVR is low or absent in most healthy tissues; however, it is overexpressed on numerous types of tumors, including colorectal cancer, glioma, myeloid leukemia, ovarian cancer, lung cancer, pancreatic cancer, melanoma, and other tumors." (PMID 39050850, 2024). "The two agonists of TIGIT, CD155 (also known as poliovirus receptor [PVR]) and CD112 (alternatively termed as PVRL2 or nectin-2), are widely expressed by immune, non-immune, and tumor cells, including melanoma cells." (PMID 38617537, 2024). "Two agonists, CD155 (poliovirus receptor-PVR) and CD112 (PVRL2, nectin-2), are expressed by immune cells, non-immune cells, and by tumor cells including melanoma." (PMID 29544515, 2018).
breast cancer (54 papers, 2004 to 2026). A primary or metastatic malignant neoplasm involving the breast. "The ligand of TIGIT, poliovirus receptor (PVR) was reported to be associated with more aggressive breast cancer subtypes such as HER2 positive and TNBC, which is consistent with our results." (PMID 33721026, 2021). "In breast cancer patients, high PVR expression is associated with poor prognosis." (PMID 39156900, 2024). "Serum-soluble PVR levels correlate with risk factors for breast cancer." (PMID 39156900, 2024). "Additionally, PVR expression is an independent poor prognostic factor for OS in patients with cholangiocarcinoma, and high PVR mRNA levels are associated with shorter OS and a recurrence-free interval in patients with breast cancer." (PMID 35625835, 2022). "Overall, these studies showed consistent results, indicating that elevated PVR expression is associated with decreased survival in patients with solid cancer, including lung cancer, esophageal cancer, cholangiocarcinoma, and breast cancer, and hematologic cancers, including AML." (PMID 35625835, 2022). "To gain deeper insights into the immune evasion mechanisms driven by TLR stimulation in 4T1 breast cancer cells, we conducted a comprehensive evaluation of the gene expression of key immune checkpoint molecules, including PD-L1, Gal-9, and PVR." (PMID 41550509, 2026). "Rb-loss reduces several ‘hallmarks’ of immune response in mouse models, and its deficiency correlates with the induction of PVR, CD274 and several other IC modulators, including ICOSLG and TNFRSF12A in human breast cancer." (PMID 37230983, 2023). "High levels of TIGIT and its ligand PVR (poliovirus receptor, CD155) are significantly associated with low overall survival and recurrence-free survival of patients with breast cancers." (PMID 36612100, 2022). "Transcriptomic analyses showed that both TIGIT and PVR are overexpressed in TNBC compared with other breast cancer types." (PMID 36544779, 2022). "No published data supports a clear definition of high and low TIGIT or PVR expression in tumors, either in breast cancer or in other tumors." (PMID 36544779, 2022). "Conversely, in a study on 197 breast cancer samples, high PVR mRNA levels were identified as an independent prognostic marker of shorter survival." (PMID 36544779, 2022). "In a series of breast cancers, including HER2+ tumors and TNBC, PVR gene expression was associated with poor clinical outcome." (PMID 36544779, 2022). "In vitro evidence support that blocking TIGIT or PVR resulted in enhanced immune cell-mediated lysis of breast cancer cell lines." (PMID 33721026, 2021). "Through the analysis of the public GEO database, the evaluated expression level of CD47 and PVR was also validated in esophageal squamous cell carcinoma, colon cancer, and breast cancer tissues in the GSE23400, GSE44076, and GSE42568, respectively." (PMID 34068552, 2021). "A recent study by Stammet al. showed that the use of an anti-PVR or anti-TIGIT monoclonal antibody (mAb) resulted in increased lysis of breast cancer cell lines by cytokine-induced killer cells." (PMID 32489646, 2020). "In vitro, Adriamycin treatment of breast cancer cell lines increases PVR expression." (PMID 39156900, 2024). "PVR showed high expression on endothelial cells, epithelial cells, fibroblasts, and cDCs in all three tumors, but only in breast cancer showed significant differences from other cell subsets, and unlike the bioinformatics results, pDCs also expressed moderate amounts of PVR." (PMID 39120585, 2024).
breast cancer (continued). "Also, In breast cancer, malignant cells can circumvent host immune responses via various mechanisms of immune evasion, including the upregulation of immune checkpoint ligands such as programmed death ligand 1 (PD-L1), PD-L2, poliovirus receptor (PVR; CD155), and galectin-9 (Gal-9)." (PMID 41550509, 2026). "CD47 and PVR were highly co-expressed on the human esophageal squamous cell lines KYSE-70 and EC9706, the colorectal cancer cell line HT29, and the breast cancer cell line MCF7." (PMID 34068552, 2021). "Both receptors recognize CD155 (also known as PVR) and CD112 (also known as Nectin-2), ubiquitous cell-adhesion molecules overexpressed in HER2+ breast cancer cell lines." (PMID 29181007, 2017). "However, this cohort combined all breast cancer subtypes, including HER2+ cancers and TNBC that represent the most aggressive breast cancer subtypes and showed the highest PVR mRNA levels, suggesting potential confounding variables." (PMID 36544779, 2022). "We focused our attention on MDAMB231 breast cancer and U87MG glioma cell lines, and we first analysed whether the SUMO pathway regulates PVR surface expression." (PMID 28874810, 2017). "Furthermore, high levels of soluble PVR are reportedly associated with poor prognosis in several cancer types, including hepatocellular carcinoma, breast cancer, and AML; however, the role of soluble PVR in MM has not been studied." (PMID 35625835, 2022).
pancreatic cancer (38 papers, 2016 to 2026). "A previous study showed high expression of poliovirus receptor (PVR) via immunohistochemistry staining of human pancreatic cancer tissues and its association with clinical outcome of the patients." (PMID 38029961, 2024). "In this study, gemcitabine upregulated the expression of MICB, ULBP1, ULBP2/5/6, ULBP3, and PVR in pancreatic cancer cell lines." (PMID 37169953, 2023). "Multiple studies have shown that PVR was overexpressed in various cancers including lung adenocarcinoma, pancreatic cancer, ovarian cancer, myeloid leukemia, neuroblastoma, rectal cancer, and cholangiocarcinoma." (PMID 36552960, 2022). "In pancreatic cancer cells, the silencing of PVR inhibited cell proliferation, and induced cell-cycle arrest at the G2/M phase." (PMID 36552960, 2022). "In support of our findings regarding the clinical significance for PVR and PVRL2 expression in AML, in pancreatic cancer patients, a high PVR expression also represented an independent prognostic factor for overall survival." (PMID 29855615, 2018). "Interestingly, enrichment of some molecules, including TGF-β1, nectin-2, and PVR, was identified in pancreatic cancer-derived EVs by Western blotting." (PMID 31234517, 2019). "Apart from TGF-β1, pancreatic cancer-derived EVs also contained multiple other immune regulatory factors, such as PVR and nectin-2, which could be delivered as inhibitory signals to NK cells." (PMID 31234517, 2019). "Therefore, in addition to TGF-β1, PVR and nectin-2 in pancreatic cancer-derived EVs could also impair NK cell function." (PMID 31234517, 2019). "By Western blotting, we found that pancreatic cancer-derived EVs displayed a variety of immune regulatory molecules, such as TGF-β1, nectin-2, and PVR." (PMID 31234517, 2019).
glioma (37 papers, 2012 to 2025). A benign or malignant brain and spinal cord tumor that arises from glial cells (astrocytes, oligodendrocytes, ependymal cells). "In glioma cells, GALNT7 was co-expressed with several gene including STAT3 which was associated with the JAK-STAT signaling pathway, PVR which participated in the CAMs pathway." (PMID 32308562, 2020). "The excellent oncolytic capacity of poliovirus PVS-RIPO coincides with its unique ability to bind with a poliovirus receptor (PVR, CD155) expressed in human glioma cells." (PMID 37445721, 2023). "Glioma prognosis was correlated to immune checkpoints LGALS9, PVR, TNFSF9 and ICOSLG." (PMID 40777122, 2025). "In glioma cells, it was observed that the expression of genes related to MRM, like GTPBP3, METTL2A, METTL6, METTL8, NSUN4, and TRMT61A, showed positive correlation with the expression of HAVCR2, PVR, TNFRSF25 and TNFSF15 as revealed by scRNA-seq analysis." (PMID 38824202, 2024). "The expression of HAVCR2, PVR, TNFRSF25, and TNFSF15 showed a positive correlation with the expression of numerous MRM-related genes like GTPBP3, METTL2A, METTL6, METTL8, NSUN4, and TRMT61A in glioma cells." (PMID 38824202, 2024).